HDAC2 (histone deacetylase 2)
Diseases named in the same sentence as HDAC2 in open-access papers (continued):
Sharing a sentence is not in itself a finding about the gene and the disease.
hepatocellular carcinoma (36 papers, 2011 to 2025). A malignant tumor that arises from hepatocytes. "HDAC2 has been implicated in the malignant phenotype of hepatocellular carcinoma via LAPTM4B activation and in cisplatin resistance in triple-negative breast cancer by modulating m6A-mediated DNA damage repair." (PMID 41444923, 2025). "It was found that elevated HDAC2 expression was detected in HepG2 (human hepatoma cell line) after HBx overexpression." (PMID 38444939, 2024). "HDAC2 promoted hepatocellular carcinoma cell proliferation by increasing the expression of cell cycle-related proteins, such as cyclin D1, cyclin-dependent kinase 4 (CDK4), and phospho-Rb." (PMID 36968022, 2023). "Previous studies have indeed demonstrated the involvement of p19INK4D in proliferative arrest after HDAC1 and HDAC2 inhibition in hepatocellular carcinoma cells, as well as the involvement of p15INK4B after treatment of HaCat cells with TSA or NaB." (PMID 34253688, 2021). "Activation of the PI3K‐AKT pathway upregulated HDAC2 expression at the mRNA and protein levels in hepatocellular carcinoma." (PMID 31993801, 2020). "FK228, which is a specific HDAC1 and HDAC2 inhibitor, was confirmed to induce cell cycle arrest in the G1/S phase in hepatocellular carcinoma." (PMID 31993801, 2020). "Depletion of HDAC1 and HDAC2 increased cell death and inhibited cell viability in hepatocellular cancer cell lines." (PMID 29945926, 2018). "Overexpression of miR-145 reduces the tumorigenic potential of hepatocellular carcinoma cells in vitro and in vivo, recapitulating the effects of HDAC2 inhibition." (PMID 29401683, 2018). "Compared with normal hepatocyte LO2 group, the expression of HDAC2 protein in urushiol derivative compound 1 group was significantly lower than that in hepatoma cell group (p < 0.05)." (PMID 29751548, 2018). "In hepatocellular carcinoma, miR-145 is down-regulated and negatively regulates the histone deacetylase 2 (HDAC2) expression." (PMID 29401683, 2018). "Next, to validate our observations in in vivo model, we prepared diethylnitrosamine (DEN)–induced liver cancer rat models and examined cell cycle molecules and HDAC2 expressions in hepatocellular carcinoma tissues." (PMID 25797269, 2015). "Aberrant regulation of HDAC2 was reported to play a pivotal role in the generation and development of many type of cancers including hepatocellular carcinoma, ovarian cancer, gastric cancer and others." (PMID 24465727, 2014). "Previous studies have shown that HDAC1 and HDAC2 are frequently overexpressed in hepatocellular carcinoma and that higher expression levels are associated with poorer survival, suggesting their potential value as prognostic biomarkers and therapeutic targets in HCC." (PMID 41458606, 2025). "However, there have been no reports of dual-targeting inhibitors for protein kinase membrane-associated tyrosine/threonine 1 (PKMYT1) and histone deacetylase 2 (HDAC2), which are critical targets for hepatocellular carcinoma treatment." (PMID 39619613, 2024). "Previous researchers found that PI3K‐AKT pathway activation could promote HDAC2 transcription and translation, accelerating the progression of hepatocellular carcinoma." (PMID 31993801, 2020). "Besides, melittin inhibited growth of human hepatoma cells through HDAC2-mediated PTEN upregulation and inhibition of PI3K/AKT signaling pathway." (PMID 30866426, 2019). "The results indicated that compound 4 is a hopeful adjuvant drug for hepatocellular carcinoma, and it could become a prospective new promising lead as an HDAC2-targeted anticancer drug; compound 10 has great prospects for being a drug." (PMID 30332739, 2018).
hepatocellular carcinoma (continued). "The expression of HDAC2 was found to be increased in human hepatocellular carcinoma and CRC." (PMID 28538837, 2017). "HDAC2 may also facilitate multiple biological behaviors in hepatocellular carcinoma." (PMID 37171044, 2023). "We have previously shown that HDAC1, HDAC2, and HDAC3 (HDAC1–3) genes encoding histone deacetylases 1–3 are upregulated in primary human hepatocellular carcinoma (HCC)." (PMID 27342975, 2016). "A study in hepatocellular carcinoma (HCC) cells has indeed demonstrated that inhibition of HDAC1 and HDAC2 triggered increased expression of p21WAF1 and p19INK4D and subsequent growth arrest." (PMID 34253688, 2021). "Using qPCR and Western blotting, we found that the mRNA and protein levels of HDAC2 in hepatocellular carcinoma cells (HepG2, Huh6, and SNU398) are higher than those in normal hepatocytes (LO2)." (PMID 36189258, 2022). "In addition, using qPCR, we found that the mRNA expression of EEF1E1 and HDAC2 in hepatocellular carcinoma cells (HepG2, Huh6, and SNU398) are higher than those in normal hepatocytes (LO2)." (PMID 36189258, 2022). "Histone deacetylase 2 (HDAC2) is crucial for embryonic development, affects cytokine signaling relevant for immune responses and is often significantly overexpressed in solid tumors; but little is known about its role in human hepatocellular carcinoma (HCC)." (PMID 22132221, 2011).
chronic obstructive pulmonary disease (34 papers, 2010 to 2025). A chronic and progressive lung disorder characterized by the loss of elasticity of the bronchial tree and the air sacs, destruction of the air sacs wall, thickening of the bronchial wall, and mucous accumulation in the bronchial tree. "HDAC2 ameliorates skeletal muscle dysfunction caused by chronic obstructive pulmonary disease (COPD) primarily through the activation of the NF-κB signaling pathway." (PMID 38148899, 2023). "The loss of HDAC2 in NKT-like cells is associated with lymphocyte senescence in chronic obstructive pulmonary disease." (PMID 28177888, 2017). "Specific knockdown of HDAC2 by RNA interference led to GC insensitivity and inhibited the association between GR and NF-κB while overexpression of HDAC2 in GC-insensitive alveolar macrophages from patients with chronic obstructive pulmonary disease is able to restore GC sensitivity." (PMID 34681832, 2021). "In the specific context of oxidative and/or nitrative stress, such as cigarette smoke, in chronic obstructive pulmonary disease (COPD), HDAC2 phosphorylation or nitration was linked to its ubiquitination and degradation by proteasome." (PMID 22414492, 2012). "PM2.5 promotes M2 polarization by inhibiting histone deacetylase 2 (HDAC2), which can lead to chronic obstructive pulmonary disease." (PMID 40231163, 2025). "miR-223 negatively correlates with HDAC2 expression in lungs from chronic obstructive pulmonary disease (COPD) patients." (PMID 35990654, 2022). "In terms of airway disease, the drug theophylline, which exerts it effects by activating HDAC2, is used to treat patients with corticosteroid resistant chronic obstructive pulmonary disease and has the potential to treat corticosteroid insensitive asthmatics." (PMID 26243279, 2015). "Furthermore, transcriptional and translational downregulation of HDAC2 has been noticed in surgically resected lung tissues of patients with severe chronic obstructive pulmonary disease." (PMID 33096729, 2020). "Reduction of HDAC2 activity in the lung is correlated with increased expression of IL-8 in chronic obstructive pulmonary disease (COPD), but its potential role during the pathogenesis of BPD remains unknown." (PMID 24595367, 2014). "For example, curcumin inhibits HDAC2 activity, thus reducing the severity of chronic obstructive pulmonary disease (COPD)." (PMID 38675577, 2024). "In patients with chronic obstructive pulmonary disease (COPD), where HDAC2 activity is impaired, the inflammatory response is often steroid-resistant." (PMID 33363465, 2020). "On the other hand, reduction in HDAC2 expression and activity leads to enhanced inflammation and reduced steroid responsiveness in chronic obstructive pulmonary disease (COPD)." (PMID 28686666, 2017). "Histone deacetylase 2 (HDAC2) is a class I histone deacetylase family member that plays a critical role in suppressing inflammatory gene expression in the airways, lung parenchyma, and alveolar macrophages in patients with chronic obstructive pulmonary disease (COPD)." (PMID 26809128, 2016). "For instance, HDAC2 and DNMT1 have significant roles in chronic obstructive pulmonary disease (COPD) progression." (PMID 33173052, 2020). "Infection by Moraxella catarrhalis, one of the reasons for exacerbation of chronic obstructive pulmonary disease, induces reduction in the levels of expression and activity of HDAC1 and HDAC2 in bronchial epithelial cells." (PMID 26697414, 2015). "The expression of HDAC2 is reported as reduced in chronic obstructive pulmonary disease (COPD)." (PMID 23717666, 2013). "As steroid suppresses the activation of pro-inflammatory genes by recruiting histone deacetylase 2 (HDAC2), a reduction in HDAC2 expression and activity had been linked with increased inflammation in chronic obstructive pulmonary disease (COPD) and bronchial asthma patients." (PMID 31191307, 2019).
chronic obstructive pulmonary disease (continued). "HDAC-2 function is impaired by oxidative stress which may be critical in the development of the uncontrolled chronic and relatively glucocorticoid insensitive inflammation seen in the lungs of patients with chronic obstructive pulmonary disease (COPD)." (PMID 20637110, 2010).
prostate carcinoma (34 papers, 2008 to 2026). A carcinoma that arises from epithelial cells of the prostate gland. "Previous studies shown that HDAC2 was upregulated in breast, colorectal and prostate cancers, and HDAC2 was associated with cancer-promoting molecular events." (PMID 36577966, 2022). "HDAC-2 overexpression has been associated with poor prognosis in patients with gastric, colorectal, hepatocellular and prostate carcinoma (especially Gleason score 7 cases), while it has been connected with prolonged survival in invasive breast carcinoma cases." (PMID 33799478, 2021). "Our survival analyses clearly demonstrate that high HDAC2 expression is associated with shortened patient relapse-free survival time in prostate cancer, which is especially prominent in the clinically important and prognostically heterogeneous subgroup of patients with Gleason 7 carcinomas." (PMID 18212746, 2008). "Moreover, it was demonstrated in some cancers that higher HDAC expression might be associated with poor prognosis—for example, in prostate carcinoma, a higher HDAC2 expression is associated with shorter relapse time." (PMID 35681732, 2022). "Additional examples include miR-212, which modulates EZH2, G9a, and HDACs in lung cancer; miR-126, targeting HDAC2 in prostate cancer; and miR-34a, which regulates SIRT1 in breast cancer." (PMID 40761244, 2025). "A study reported that RA treatment prompted cell cycle arrest and apoptosis in prostate cancer cell lines by influencing the expression of Histone Deacetylase 2 (HDAC2)." (PMID 37836581, 2023). "RA induced cell cycle arrest and apoptosis through modulation of HDAC2 expression in prostate cancer." (PMID 37764768, 2023). "Enhanced angiogenesis induced by chronic stress and β-adrenergic signaling via histone deacetylase-2 (HDAC2)-mediated suppression of thrombospondin-1 was also observed in a stressed model of prostate cancer." (PMID 34869378, 2021). "In prostate cancer, it induced apoptosis and cell cycle arrest through the modulation of HDAC2 expression." (PMID 32503209, 2020). "HDAC2 induced by beta-adrenergic signaling promoted tumor angiogenesis and prostate cancer progression by suppressing thrombospondin-1 expression." (PMID 32292495, 2020). "Induction of HDAC2 by CREB1 is critical for prostate cancer progression promoted by chronical bio-behavioral stress that activates PKA-CREB1 pathway though beta adrenergic signaling." (PMID 32039001, 2019). "Overexpression of HDAC2 was reportedly correlated with a more advanced stage in gastric carcinoma and it was also a prognostic indicator for a poor outcome in cases of prostate carcinoma." (PMID 23420051, 2013). "This not only hints at an important role of this isoform in prostate cancer progression but also suggests HDAC2 expression as a novel prognostic marker for prostate cancer." (PMID 18212746, 2008). "Notably, HDAC1 and HDAC2 are associated with Gleason grade and recurrence‐free survival (RFS) in prostate cancer." (PMID 41200281, 2025). "Furthermore, silibinin caused a modest, concentration-dependent increase in overall DNA methyltransferase activity, a decrease in HDAC1 and HDAC2 expression levels, and was associated with EMT and cancer stem cell phenotypes in prostate cancer." (PMID 41226811, 2025). "However, the finding that HDAC2 is an independent prognosticator in prostate cancer ought to be verified in a larger prospective study." (PMID 18212746, 2008). "Indeed, the oncogenic role of HDAC2 has been confirmed in prostate cancer." (PMID 37528657, 2023). "It is still unknown whether HDAC2 is involved in NE phenotype regulation in prostate cancer." (PMID 32039001, 2019).
prostate carcinoma (continued). "Taken together, our data suggest that rs78835907 G allele alters the binding affinity of HDAC2 to the DNA, which in turn reduces the expression of ATG16L1, consequently contributing to the more aggressive phenotype and poorer clinical outcome in prostate cancer." (PMID 26365175, 2015). "In addition, HDAC2 was an independent prognostic marker in our prostate cancer cohort." (PMID 18212746, 2008). "HDAC2 knockdown also abolished DHT repression of IKBKE in LNCaP cells, a different AR prostate cancer cell line." (PMID 41542764, 2026). "MiR-34b affects HDAC1, HDAC2, and HDAC4 in prostate cancer, while miR-127, miR-411, miR-431, and miR-432 are implicated in HDAC regulation in osteosarcoma." (PMID 40761244, 2025). "Chidamide, in contrast, selectively targets HDAC1, HDAC2, HDAC3, and HDAC10, aligning closely with the four HDAC isoforms most overexpressed in prostate cancer, making it a more biologically relevant candidate for mCRPC treatment." (PMID 41200281, 2025). "Previous evidence has suggested that HDAC2 is necessary for both beta-adrenergic signalling and CREB activation to promote prostate cancer cells proliferation." (PMID 37528657, 2023). "After CREB activation by β-AR, histone deacetylase 2 (HDAC2) epigenetically inhibits thrombospondin-1 (TSP1), a potent angiogenesis inhibitor, thereby promoting angiogenesis and prostate cancer progression." (PMID 36707854, 2023). "We analyzed the expression of DNMT1, DNMT3A, DNMT3B, and the class I HDACs HDAC1, HDAC2, HDAC3, and HDAC8 in the PRAD and Taylor data sets and their correlation to HLA-I expression in prostate cancer." (PMID 36050516, 2022). "Weichert and colleagues demonstrated that HDAC1, HDAC2, and HDAC3 are overexpressed in prostate cancers, whereas increased expression of HDAC1 and HDAC2 correlates with higher Gleason scores." (PMID 33572730, 2021). "Histone deacetylase-2 (HDAC2) epigenetically represses the expression of THBS1, consequently inducing angiogenesis in prostate cancer." (PMID 31847842, 2019). "For example, compound 11b, an indomethacin-SAHA fusion molecule that selectively inhibits COX2 and HDAC6 > HDAC8 > HDAC3 > HDAC2 > HDAC1, inhibits the proliferation of androgen-dependent prostate carcinoma cells." (PMID 31561534, 2019). "Meta-analysis of prostate cancer TCGA database revealed a negative correlation between HDAC2 and IKBKE mRNA expression." (PMID 41542764, 2026). "DIM inhibits HDAC2 activity, which may contribute to the DIM-induced increase in p21 expression in prostate cancer cells." (PMID 41226811, 2025). "Additionally, Histone deacetylase-2 (HDAC2) inhibited the expression of THBS1, leading to the stimulation of angiogenesis and the acceleration of prostate cancer development via beta-adrenergic signaling." (PMID 39273281, 2024). "Moreover, histone deacetylase-2 (HDAC2) suppressed THBS1 expression, subsequently induced angiogenesis, and promoted prostate cancer progression mediated by beta-adrenergic signaling." (PMID 38203613, 2023). "In addition, expression of HDAC1 (P=0.032), HDAC2 (P=0.002) and HDAC3 (P<0.001) correlated significantly with the Ki-67-positive proliferative fraction of prostate cancer cells." (PMID 18212746, 2008).